PTGS2 (prostaglandin-endoperoxide synthase 2)
Diseases named in the same sentence as PTGS2 in open-access papers (continued):
Sharing a sentence is not in itself a finding about the gene and the disease.
cancer (continued). "Other studies have reported that the overexpression of PTGS2 and the accumulation of its by-product prostaglandin E2 (PGE2) within hypoxic regions of several types of tumors are associated with the increased recruitment and M2-like polarization of macrophages that lead to poor cancer outcomes." (PMID 30788287, 2019). "PTGS2 might play an active role in radiotherapy tolerance of cancer." (PMID 30740906, 2019). "Similarly, to investigate the effect of NSAID use on the risk of cancer, we can calculate the crude pooled OR (OR = 0.807, 95% CI = 0.732–0.890, P < 0.001, not shown in the tables) because the PTGS2 rs5275 polymorphism did not have an influence on this risk." (PMID 29552297, 2018). "Use of aspirin or non-aspirin NSAIDs at anti-inflammatory/analgesic doses may affect cancer progression by inhibiting prostaglandin endoperoxide synthase-2 (PTSG-2, cyclooxygenase-2) dependent mechanisms involved in cancer cell proliferation, motility, invasion and angiogenesis." (PMID 24708725, 2014). "Mechanistic studies revealed FS targets key molecules (STAT3, EGFR, ESR1, PTGS2, NF-κB1, and JUN), modulating PI3K-Akt, MAPK and cancer-related pathways." (PMID 40649400, 2025). "In contrast, seven out of ten anti-AD core targets (PTGS2, MAPK1, MAPK3, JUN, ESR1, IL6, and PIK3CA) followed the pathways in cancer." (PMID 40179089, 2025). "Protein–protein interaction networks identified hub genes for each cancer type, with key shared targets including EGFR, ESR1, PTGS2, and STAT3." (PMID 41155677, 2025). "Prostaglandin-endoperoxide synthase 2 (PTGS2), also known as cyclooxygenase-2 (COX-2), mediates resistance by fostering an immunosuppressive microenvironment, promoting angiogenesis, and supporting cancer stem cell populations." (PMID 39309859, 2024). "There is insufficient research on the PTGS2, CASP3, ESR1, and BCL2 targets in cancer-induced fatigue." (PMID 39564104, 2024). "Cancer stool samples showed increased levels of IL1B, IL8, and PTGS2 transcripts compared to polyp and control groups." (PMID 39523395, 2024). "The expression of PTGS2 and KDR was significantly higher in stage 3 and stage 4 cancer, respectively." (PMID 38426619, 2024). "NSAIDs like Diclofenac, Mefenamic acid, Celecoxib, Naproxen, and Etoricoxib showed high binding affinity to PTGS2, indicating their potential to suppress TDM-1-resistant cancer cells by modulating inflammation and immune responses." (PMID 39309859, 2024). "Key targets such as TNF, PTGS2, PRKACA, HSP90AB1, RELA, and NFKBIA appeared to be involved in chemical carcinogenesis–receptor activation, pathways in cancer, IL-17 signaling pathway, cholinergic synapse pathway, and regulation of lipolysis in adipocytes." (PMID 39064924, 2024). "PTGS2 also known as COX2, is a prognostic marker for renal cancer and plays multiple roles in cancer cell resistance to chemotherapy and radiotherapy." (PMID 39346898, 2024). "Prostaglandin endoperoxide synthase 2 (COX-2) releases prostaglandins and increases inflammation in cancer." (PMID 39597528, 2024). "This analysis confirmed that PTGS2 and PTGES2 are the central genes through which aspirin impacts cancer survival." (PMID 38201650, 2024). "All the studied genes involved in inflammation (MMP9, PTGS2, TNF-α, and IL-6R) were expressed by cancer cells." (PMID 39072314, 2024). "From the functional annotation analysis, CDKN2A, VEGFA, PTGS2, and STAT1 were involved in cancer pathways (hsa05200; KEGG pathway)." (PMID 36765810, 2023). "We noted that the expression levels of PTGS2 and CTLA4 were highly heterogeneous across various cancer types." (PMID 38201508, 2023). "The expression levels of genes involved in cancer invasiveness (MYC, VEGFB, IL33, PTGS2, and PTGER2) were increased." (PMID 37601099, 2023). "For 3/5 of the CTX drugs, there was a significant inverse correlation between the sensitivity of the cancer cells to the drug (expressed as the mean 50% growth inhibitory concentration, GI50) and PTGS2 induction." (PMID 35440553, 2022).
cancer (continued). "In general, the immune checkpoints seem to express with more activeness in the low-PTGS2 group, except for CD276, whose expression is always found upregulated in malignant tumors and accompanied with a poorer prognosis for cancer patients." (PMID 35432535, 2022). "The targets in the cancer pathways (SRC, EGFR, ESR1, PTGS2, and APP) were used for molecular docking analysis with all active compounds." (PMID 36561345, 2022). "AKT1, EGFR, SRC, ESR1, and PTGS2 are the top five targets in the PPI network, and they were reported as critical regulatory factors in cancer metastasis and EMT." (PMID 35942366, 2022). "In fact, in addition to PTGS2, the mRNA expression of AR was also significantly upregulated in PDAC samples (and other five cancers) compared with normal samples (FC > 1.6, p < 0.01)." (PMID 35701649, 2022). "The abnormal expression of targets (IL6, MAPK1, PPARG, PTGS2, and MAPK3) leads to cell proliferation and a variety of cancer types." (PMID 35992697, 2022). "Of note, we identified PTGS2 as a downstream target of MAEL and a key mediator of MAEL-dependent cancer stemness through AKT activation." (PMID 35740546, 2022). "A total of five cancer-related genes (BDNF, PTGS2, CTNNB1, GSK3B, and HPGD) were selected based on the Gene Ontology database." (PMID 35054980, 2022). "More sensitive cancer cell lines, with a lower GI50, were those which typically displayed enhanced PTGS2 expression after treatment." (PMID 35440553, 2022). "Following RARβ silencing, the down-regulation of cancer-related genes, ALDH1A1, CYP24A1, BIRC5, EDN1, IL-1β and PTGS2 in A549 parental cell suggest the importance of RARβ in controlling the expression of genes related to carcinogenicity." (PMID 33995625, 2021). "Of note, etanercept demonstrated marked inhibition of genes involved in LPS-mediated tissue injury and possibly a role in the process of transformation of normal epithelial cells to cancer cells, such as MMP-1 and PTGS2." (PMID 34648530, 2021). "Paradoxically, we found a reduced accumulation of arachidonic acid-derived metabolites, including prostaglandin 2, as well as a reduced expression of COX2/PTGS2 and PTGES transcripts in cancer tissue." (PMID 33322148, 2020). "Then, 58 cancer-related targets and 66 KEGG pathways were identified, and PTGS2-, HSP90-, EGFR-, MMP2-, PPARγ-, and GSTP-mediated pathways were predicted to be the antitumor mechanisms of HD-SB." (PMID 32265701, 2020). "It had considerable “protective” anti-cancer properties and concomitantly down regulated EGFR, HER-2 and PTGS-2 (COX-2), while having significant anti-CRC effects on CRC mice models." (PMID 32401801, 2020). "Out of these, RHOB, VDR, and PTGS2 were the only candidates with FDA-approved anti-cancer drugs, with one each for RHOB and VDR, and 20 for PTGS2." (PMID 30842898, 2019). "Pro-inflammatory cytokines, in particular TNF-α and IL-6, trigger the production of cyclooxygenase 2 (COX2 or PTGS2), which in turn produces prostaglandin E2 (PGE2), favoring cancer progression." (PMID 31766196, 2019). "In these networks, PTGS2, VDR, RHOB, PIM1, HSPA1L, HSPA1A, and SPHK1 were used as targets for cancer drug development, previously." (PMID 30842898, 2019). "Considering that miR-125b targets a wide spectrum of genes including PTGS2 and ETS1, and that miRNAs are proposed as tools for cancer therapy, we tested miR-125b alone or in combination with NS-398, a specific chemical inhibitor of PTGS228." (PMID 29700305, 2018). "Studies have shown that PI3K upregulation also enhances prostaglandin-endoperoxide synthase-2 (PTGS2, also known as cyclooxygenase-2) activity and prostaglandin E2 synthesis, which promotes cancer cell proliferation and inhibits apoptosis." (PMID 29152088, 2017). "Pathway results showed that seed genes PTGS2, HDAC1, JUN, and SLC2A1 were enriched in pathway in cancer, seed genes HDAC1 and CDC20 were involved in cell cycle, and seed gene MTHFR participated in methane metabolism." (PMID 27034707, 2016).
cancer (continued). "The AUCs ranged from 0.85 (PTGS2) to 0.99 (GSTP1), confirming cancer-specific methylation, with GSTP1 methylation as the best classifier." (PMID 26086362, 2015). "We identify cyclooxygenase 2/prostaglandin-endoperoxide synthase 2 (COX-2), a pathogen-induced enzyme involved in prostaglandin synthesis, as mediator of resistance to the effector phase of antigen-specific cancer immunity." (PMID 25501829, 2014). "The genes validated in this study – PTGS2, IL8, IL23A, TACC2 and PI3 – were selected based upon their differential response to treatment and their implication for cancer initiation." (PMID 24848801, 2014). "Apart from IL8, the co-regulation between NF-κB and AP1, CEBPB or STAT3 for genes IL1B, ICAM1, IL6, PTGS2, and SAA1 in the TF regulatory networks is consistent with previous observation in HNSCC or other cancer cells." (PMID 24069219, 2013). "The modulation of pathways involved in cancer metastasis (MMP9), inflammation (PTGS2), cell survival (AKT1), and DNA repair (PARP1) suggests that these compounds could serve as multitargeted therapies, providing an advantage over single-target drugs." (PMID 40283891, 2025). "Developing a comprehensive biomarker panel that includes PTGS2, PIK3CA, and HLA class I antigens could revolutionize the duration, dosing, and customization of aspirin therapy for cancer patients." (PMID 39445288, 2024). "However, of those genes included in the pPRS score, prior evidence links NSAID anti-cancer activity with β-catenin (CTNNB134–37), GNAS38, and PTGER419, the extracellular receptor for PGE2, the major downstream prostanoid produced by PTGS-2." (PMID 39763728, 2024). "Numerous nonsteroidal anti-inflammatory medications target PTGS2, which is increased during inflammation; as a result, improper regulation of this gene is connected to the development of cancer and cardiovascular events." (PMID 37719850, 2023). "Interestingly, however, the rise in PGE2 occurred exclusively in cancer cells that have detectable baseline levels of PGE2 and Ptgs2." (PMID 35440553, 2022). "PTGS2, also named COX-2, is a crucial target to prevent progression in various cancer types." (PMID 36304989, 2022). "In addition, Il18, Tnf, Ptgs2, Cd47, Cxcl1, and Csf1 were more highly expressed in STOSE tumors, including in the cancer cells, supporting the influence of TAMs in these tumors." (PMID 36311166, 2022). "PTGS2 had not tightly relationship with the regulators of invasion/migration, angiogenesis, and lymph-angiogenesis/lymph node metastasis in cancer." (PMID 35096012, 2021). "To provide further evidence, we isolated primary carcinoma cells from two human CRC specimens and found that TFF3 induced PTGS2 expression in a dose-dependent manner, which could be blocked by niclosamide." (PMID 34262017, 2021). "Another hub gene, such as KITLG, PTGS2, SYK, FLT1 (VEGFR-1), GNA13, etc. could also regulate invasion and metastasis of cancer 42-48." (PMID 32194783, 2020). "Prostaglandin-endoperoxide synthase 2 (PTGS2) or Cyclooxygenase-2 (COX2) is an enzyme involved in inflammation and tissue damage responses, which could lead to cancer." (PMID 32338278, 2020). "Several core components of PG could interact with PTGS2 and CASP3, potentially promoting cancer cell apoptosis through specific signaling pathways such as MAPK signaling pathway and P13K-AKT signaling pathway in order to cure LC." (PMID 33643040, 2020). "In addition, elevated coexpression of PTGS2 and NOS2 (51% and 48% of the total compounds, respectively) proteins is a strong predictor of poor survival among cancer patients." (PMID 31949474, 2019). "Fifteen members of cancer pathways, including FOS, TGFα, FZD8, MMP1, laminin subunit gamma 2, PTGS2, laminin subunit beta 3, ITGA2, laminin subunit alpha 3, VEGFC, WNT2B, heat shock protein 90 beta family member 1, WNT5B, FGF5 and WNT3A, were up-regulated in the MC group." (PMID 30482199, 2018).
cancer (continued). "Notably, PTGS2 (COX-2) and IL1B, involved in prostaglandin production supporting cancer progression and metastasis, were the most highly overexpressed genes in EBV(-) tumors (270-fold, p<0.001; and 24-fold, p=0.06, respectively)." (PMID 30400822, 2018). "Moreover, some of markers were related to cancer progression, like IGF2, PTGS2, WNT3A, according to our literature review." (PMID 28415743, 2017). "In addition to targeting CCND3, hsa-miR-16-5p is also known to regulate the expression of various angiogenic (e.g., PTGS2, VEGF, FGFR) and/or carcinogenic factors (e.g. EGFR, BMP7, MAPKs) with key roles in cancer/disease signaling pathways." (PMID 26930275, 2016). "Importantly, MSH6, PTGS2, HDAC1, JUN, SLC2A1, and MMP1 were enriched in the pathway in cancer, of which MSH6 and MMP1 were candidate genes." (PMID 27034707, 2016). "Hypermethylation of APC, CCND2, GSTP1, PTGS2 and RARB was highly cancer-specific." (PMID 26086362, 2015). "In addition, we show that the transcripts of some cancer markers, such as ALDH1A3 and PTGS2, are increased at both early and late stages of tongue carcinogenesis." (PMID 26110572, 2015). "The expression of COX-1 is constitutive in normal tissue unlike COX-2 (PTGS2), the expression of which is induced only in inflamed tissue or cancer." (PMID 25927723, 2015). "Second, PTGS2 (prostaglandin-endoperoxide synthase 2; protein product is COX2) was significantly upregulated in CITED1-expressing WiT49 cells on the gene expression microarray and was then validated on the real-time PCR cancer drug target array." (PMID 24481423, 2014). "For PTGS2 rs20417, NSAID use significantly decreased cancer risk compared with non-NSAID use in individuals homozygous for the major allele (GG) (OR = 0.82, 95% CI = 0.70–0.95)." (PMID 23967159, 2013). "For PTGS2 rs5275, NSAID users significantly decreased the cancer risk compared with non-NSAID users homozygous for the major allele (TT) (OR = 0.77, 95% CI = 0.66–0.89)." (PMID 23967159, 2013). "Furthermore, miR-26b has been shown to directly silence PTGS2 and regulate PTGS2 expression in desferrioxamine (DFOM)-treated carcinoma of nasopharyngeal epithelial (CNE) cells." (PMID 23374284, 2013). "Additionally, PTGS2, as prostaglandin–endoperoxide synthase 2, is responsible for generating prostaglandins such as prostaglandin E2 (PGE2), which play regulatory roles in various cancers." (PMID 40643495, 2025). "However, of those genes included in the pPRS score, prior evidence links NSAIDs anti-cancer activity with β-catenin (CTNNB1), GNAS, and PTGER4, the extracellular receptor for PGE2 that is the major downstream prostanoid produced by PTGS-2." (PMID 40763299, 2025). "The negative correlation between 17p genes and PTGS2 was consistent with our hypothesis that the cyclooxygenase pathway of AA metabolism was upregulated in del(17p) cancers." (PMID 36750552, 2023). "PTGS2 and PGE2 inhibition may be useful to augment cancer immunotherapy." (PMID 35411258, 2022). "Therefore, invalidating Ptgs2 in BRAFV600E melanoma could be an effective strategy to improve the NK-dependent recruitment and functions of DC1 in the cancer immune control." (PMID 35945203, 2022). "Thus, the bioactive compounds from FA and their interactions with PTGS2, HSP90, CDK6, caspase 3, Bcl-2, and MMP9 may be key in the treatment of cardiovascular disease and various cancers." (PMID 33542744, 2021). "REM sleep loss also affected several genes such as prostaglandin-endoperoxide synthase (Ptgs2), B-cell lymphoma 2 (Bcl-2), Proto-Oncogene, Tyrosine Kinase receptor (Kit), KRAS Proto-Oncogene (K-Ras), and Fos Proto-Oncogene (Fos), which are marked in cancer pathways." (PMID 33114225, 2020). "Prostaglandin-endoperoxide synthase 2 (prostaglandin G/H synthase and cyclooxygenase) (PTGS2), whose upregulation is associated with carcinogenesis and cancer progression, was not expressed in any of the three kidney regions (NOR, PTA, PTB) but was turned on in CWM (AVE(CWM) = 0.49)." (PMID 33302383, 2020).
cancer (continued). "ZIC2 e OVOL1 podem funcionar no carcinoma nasofaríngeo almejando-se de maneira significativa os genes suprarregulados (como o PTGS2, FN1, CXCL9 e CXCL10) na rede reguladora de fator de transcrição - genes diferencialmente expressos (p.ex., ZIC2→PTGS2 e OVOL1→CXCL10)." (PMID 27765529, 2017). "In addition, there was the lack of specificity for cancer type in our analysis because few studies have investigated the effect of associations between polymorphisms in PTGS1 and PTGS2 genes and NSAID use on cancer risk." (PMID 23967159, 2013). "Thus, the results of the meta-analysis among the 8 studies indicate that NSAID use significantly decreased cancer risk compared with non-NSAID use, despite the PTGS2 polymorphism." (PMID 23967159, 2013). "Thus, the results of the meta-analysis among the 7 studies also indicate that NSAID use significantly decreased cancer risk compared with non-NSAID use, regardless of the PTGS2 polymorphism." (PMID 23967159, 2013). "Several studies have investigated whether the polymorphisms in the prostaglandin endoperoxide synthase 1 (PTGS1) and PTGS2 genes and nonsteroidal anti-inflammatory drug (NSAID) use are associated with cancer risk; however, those studies have produced mixed results." (PMID 23967159, 2013). "Positive correlation with cancer-promoting genes BCL2, BCLxL, HIF1A, VEGFA, ACTA2, CCL2, PTGS2, and CDKN1A, but not Ki67, was demonstrated, particularly for ILs’ receptors." (PMID 32512917, 2020). "PTGS2, FN1, CXCL9, CXCL10, ZIC2 e OVOL1 podem desempenhar alguns papéis no carcinoma nasofaríngeo." (PMID 27765529, 2017). "Most slides from cancer-free tissue lacked expression of CCND1, CD44, CDH1, EGFR, ERBB2, KIT, keratins, NOTCH1, PAK1, PTGS2, SNAI1, and VIM but showed staining of MUC1, HIF1A, NKX2-1, SFTPC, and STAT3, which were also found in AdCa." (PMID 23028920, 2012). "However, no significant changes were seen in COX-2 (PTGS2 gene) expression, despite COX-2’s well-established role in the inflammation-carcinoma sequence in various epithelial cancers." (PMID 39062733, 2024). "The coculture of the four cancer cell lines with platelet-derived mEVs of CRC patients significantly induced PTGS2, mainly at 24 h; in contrast, mEVs of HS did not significantly affect PTGS2 gene expression." (PMID 36672299, 2023).